CCNG2 (cyclin G2)
Description:
May play a role in growth regulation and in negative regulation of cell cycle progression.
Tractability: PROTAC: ubiquitination databases record sites on it.
Gene: Protein-coding gene on chromosome 4 (77,157,207 to 77,433,388, forward strand). Ensembl gene ENSG00000138764.
Subcellular location: Cytoplasm
Subcellular location (Human Protein Atlas): Cytosol; Nucleoplasm
Pathways (Reactome):
Gene expression (Transcription): FOXO-mediated transcription of cell cycle genes
Gene Ontology:
Molecular function: cyclin-dependent protein serine/threonine kinase regulator activity
Cellular component: cyclin-dependent protein kinase holoenzyme complex; cytoplasm
Genetic constraint (gnomAD): Loss-of-function variants: 10 observed, 26.57 expected, observed/expected ratio (o/e) 0.38, 90% interval 0.23 to 0.64. The upper end of that interval is the gene's LOEUF score, 0.64, which puts it in group 2 of 6, group 1 being the genes least tolerant of losing a copy. Missense variants: 286 observed, 341.11 expected, observed/expected ratio (o/e) 0.84, 90% interval 0.76 to 0.93. Synonymous variants: 130 observed, 123.47 expected, observed/expected ratio (o/e) 1.05, 90% interval 0.91 to 1.22.
Homologues: Orthologues: chimpanzee CCNG2 (100% identical), macaque CCNG2 (99% identical), dog CCNG2 (94% identical), guinea pig CCNG2 (93% identical), pig CCNG2 (93% identical), rat Ccng2 (90% identical), rabbit CCNG2 (90% identical), mouse Ccng2 (89% identical), tropical clawed frog ccng2 (75% identical), zebrafish ccng2 (58% identical), Caenorhabditis elegans cyd-1 (17% identical), Drosophila melanogaster CycE (16% identical), and 10 more. Paralogues in human: CCNG1 (44% identical), CCNI (28% identical), CCNI2 (20% identical), CCNJL (16% identical), CCNA1 (16% identical), CCNA2 (16% identical), CCNB1 (16% identical), CCNE2 (16% identical), CCNF (16% identical), CCNB2 (16% identical), CCND3 (15% identical), CCNE1 (15% identical), and 6 more.
Diseases named in the same sentence as CCNG2 in open-access papers:
CCNG2 is named in the same sentence as 55 diseases in open-access papers, as found by Europe PMC text mining. Sharing a sentence is not in itself a finding about the gene and the disease. The quoted sentences say what the papers report.
breast carcinoma (26 papers, 2005 to 2025). "Previous studies showed that lost of cyclin G2 expression was associated with the development of gastric, ovarian, and breast cancers, but activation of Wnt/β-catenin signaling indicated a potential link between them." (PMID 24595300, 2014). "CNOT7 and its paralog CNOT8 can influence the stability of cell cycle-related genes MSMB, PMP22, and Cyclin G2 through their deadenylation ability, promoting cell proliferation in breast cancer." (PMID 41249119, 2025). "Overexpression of ExomiR-1246 is also seen to influence tumour cell proliferation and invasion in breast cancer cell lines as it suppresses the expression level of the target gene CCNG2 in MDA-MB-231 cells, an epithelial human breast cancer cell line." (PMID 38455764, 2024). "For instance, miR-1246 targets CCNG2 directly and functions as a tumor-promoter role in breast cancer." (PMID 33893245, 2021). "For example, miR-1246 induced cell proliferation and invasion, as well as drug resistance, by targeting CCNG2 in breast cancer and pancreatic cancer." (PMID 31013711, 2019). "A large body of evidence indicates that cyclin G2 is an important contributor to suppress the development of cancer; the expression of cyclin G2 is downregulated in thyroid, oral, and breast cancer." (PMID 30420966, 2018). "Ectopically inducible cyclin G2 expression was shown to potently inhibit the proliferation of breast cancer cells." (PMID 26046133, 2015). "Corresponding our data CCNG2 was identified as direct target of miR-1246 in oral squamous cell carcinoma, laryngeal squamous cell carcinoma, ovarian cancer, pancreatic carcinoma, colorectal cancer and breast cancer." (PMID 39285403, 2024). "For instance, miR-1246 could promote proliferation, invasion, and chemoresistance of breast cancer cells by targeting CCNG2." (PMID 34497267, 2021). "Similarly, exosomal miR-1246 from breast cancer cells can suppress the expression of its target gene, Cyclin-G2 (CCNG2), enhancing the viability and migration in normal epithelial cells." (PMID 32764376, 2020). "These genes, including ALCAM, ARL6IP1 and CCNG2 may play a protective role in breast cancer." (PMID 37644433, 2023). "Previous studies showed G2/M cell-cycle arrest induced by upregulation of CCNG2 and BTG2 in human breast cancer cells." (PMID 31758045, 2019). "We focused on those genes that inhibit metastasis in breast cancer including SHARP-1 and the ERα-regulated CCNG2 and the pro-metastatic factor Follistatin." (PMID 26871946, 2016). "For example, CCNG2 was a primary target gene of estrogen-occupied estrogen receptor and that its expression was rapidly down-regulated by estrogens in MCF-7 breast cancer cells." (PMID 25888956, 2015). "Metastatic breast cancer cells (MBC) could secrete and transport miR-1246 to mammary epithelial cells and nonmetastatic breast cancer cells to suppress the expression of cyclin-g2, thereby enhancing survival rates and mobility of breast cancer cells." (PMID 34475958, 2021). "These previous reports and our findings suggest that, in human breast cancer MCF-7 cells, cyclin G2 may be a key negative regulator of cell cycle progression." (PMID 16457690, 2005).
pancreatic cancer (15 papers, 2016 to 2024). "For example, miR-1246 inhibits CCNG2 expression, causing drug resistance and stemness in pancreatic cancer cells." (PMID 34226586, 2021). "The expression levels of miR-1246 were reported to be associated with CCNG2-mediated chemoresistance and stemness in pancreatic cancer cells." (PMID 29100367, 2017). "miR-1246 expression functioned importantly in chemoresistance and stemness in pancreatic cancer through interacting with CCNG2." (PMID 34497267, 2021). "MYC and HDAC2 repress Cyclin G2 (CCNG2), which ordinarily blocks the progression of the cell cycle, in neuroblastoma and pancreatic cancer cells to drive proliferation." (PMID 28505071, 2017). "We previously showed that drug sensitivity of pancreatic cancer cells is correlated with expression of miR-1246, which targets CCNG2 mRNA and decreases CycG2 protein levels." (PMID 27982046, 2016). "Additionally, the miR-1246 expression was associated with chemoresistance and cancer stem cell-like properties via cyclin-G2, and predicted a worse prognosis in pancreatic cancer patients." (PMID 34112884, 2021). "In addition, in pancreatic cancer cells as well as a mouse model, MIR1246 expression was associated with cancer cell stemness and chemoresistance by targeting cyclin G2 (CCNG2)." (PMID 32457495, 2020). "In addition, a study on the interaction of miR-1246 with CCNG2 in pancreatic cancer found that a high expression of miR-1246 was correlated with a worse prognosis and that CCNG2 expression was significantly lower in those patients." (PMID 29720957, 2018). "CCNG2 deeply involved in progression of pancreatic cancer via cell proliferation, invasion, chemoresistance, and differentiation, but this gene might be responsible for cell proliferation, invasion, chemoresistance, and differentiation in pituitary prolactinoma." (PMID 33709028, 2021).
gastric cancer (11 papers, 2018 to 2025). A primary or metastatic malignant neoplasm involving the stomach. "Downregulation of CCNG2 has also been linked to more aggressive disease and metastasis in gastric cancer." (PMID 39118790, 2024). "Another study investigated the effects of Cyclin G2 overexpression in gastric cancer cells and found that it causes the inhibition of proliferation." (PMID 36769170, 2023). "Accumulating evidence showed that CCNG2 expression has an inverse association with the development of various cancers, such as breast, lung, colorectal, and gastric cancers." (PMID 34497267, 2021). "The aim of this study is to investigate the role and the underlying mechanisms of cyclin G2 on Wnt/β-catenin signaling in gastric cancer." (PMID 30547803, 2018). "In summary, this study established that cyclin G2 suppresses Wnt/β-catenin signaling in gastric cancer, acting through association with and impact Dpr1 phosphorylation to stimulate β-catenin degradation in a GSK-3β-dependent manner." (PMID 30547803, 2018). "Using GSK-3β inhibitors and a GSK-3β-mediated β-catenin phosphorylation site mutation AGS cell line, we revealed that cyclin G2 inhibited gastric cancer proliferation and migration through the Wnt/β-catenin signaling." (PMID 30547803, 2018). "TCGA datasets were used to evaluate the association between cyclin G2 expression and the prognostic landscape of gastric cancers." (PMID 30547803, 2018). "Based on the findings above, we explored the underlying molecular mechanisms through which cyclin G2 reduced the progression of gastric cancers." (PMID 30547803, 2018). "We found that cyclin G2 levels were decreased in gastric cancer tissues and were associated with tumor size, migration and poor differentiation status." (PMID 30547803, 2018). "According to this study’s findings, LINC00460 influences gastric cancer cell proliferation and apoptotic activity via the downregulation of CCNG2 and recruiting LSD1 and EZH2." (PMID 38850527, 2024). "Cyclin G2 is downregulated in gastric cancer and is regulated via miR-340 which is overexpressed and promotes gastric cancer." (PMID 36769170, 2023). "Cyclin G2 was observed in gastric cancer patients with an exception of female patients, where it was recorded as being lower, and the overall expression was inversely correlated with advanced stages of gastric cancer." (PMID 36769170, 2023). "Another study explored Cyclin G2 in gastric cancer and observed decreased Cyclin G2 expression in gastric cancer tissues." (PMID 36769170, 2023). "Cyclin G2 inhibited the activity of CKI to phosphorylate DACT1, causing growth arrest in gastric cancer cells." (PMID 35864965, 2022). "It has been observed that CCNG2 levels are inversely correlated with cancer progression in breast, thyroid, oral, and gastric cancers, and in acute leukemia." (PMID 31013711, 2019). "In the present study, we show that cyclin G2 was downregulated in clinical gastric cancer tissue and exerted inhibitory effects on proliferation and migration of gastric cancer cells in vitro and in vivo." (PMID 30547803, 2018). "The effects of ectopic and endogenous cyclin G2 on the proliferation and migration of gastric cancer cells were assessed using the MTS assay, colony formation assay, cell cycle assay, wound healing assay and transwell assay." (PMID 30547803, 2018). "Real-time PCR, immunohistochemistry and in silico assay were used to determine the expression of cyclin G2 in gastric cancer." (PMID 30547803, 2018). "Low mRNA and protein expression of cyclin G2 in gastric cancer indicated that cyclin G2 is involved in the progression of gastric cancers." (PMID 30547803, 2018). "This study demonstrates the inhibitory function of cyclin G2 in gastric cancer proliferation and migration through the Wnt/ β-catenin signaling and explored the underlying mechanisms." (PMID 30547803, 2018).
gastric cancer (continued). "We previously reported that cyclin G2 inhibited osteogenesis through Wnt/β-catenin pathway, which also contributed to the development of gastric cancer." (PMID 30547803, 2018). "Collectively, our results suggested that cyclin G2 suppresses the Wnt/β-catenin signaling and inhibits gastric cancer cell growth and migration through Dapper1." (PMID 30547803, 2018). "Low level of cyclin G2 expression was also shown in immunoblotting assay in gastric cancer compared with normal gastric tissues." (PMID 30547803, 2018). "We previously showed that overexpression of cyclin G2 inhibited gastric cancer cell growth in liquid cultures and in soft agar." (PMID 30547803, 2018). "Taken together, cyclin G2 negatively regulated the proliferation and migration of gastric cancer cells in vivo and in vitro." (PMID 30547803, 2018). "In contrast, Chen gastric (132 samples) and Cho gastric (90 samples) datasets showed an increased cyclin G2 expression in gastric cancers." (PMID 30547803, 2018). "Taken together, we can conclude that cyclin G2 inhibits gastric cancer proliferation and migration and suppresses Wnt/β-catenin signaling through Dpr1." (PMID 30547803, 2018). "Down-regulation of cyclin G2 mRNA was observed in 33 of the 45 gastric cancer samples compared with paired normal tissues." (PMID 30547803, 2018). "This study demonstrates that cyclin G2 suppresses Wnt/β-catenin signaling and inhibits gastric cancer cell growth and migration through Dapper1." (PMID 30547803, 2018). "In this study, the role of cyclin G2 in gastric cancer in vitro and in vivo mediated by Wnt/β-catenin signaling was determined." (PMID 30547803, 2018). "Taken together, this work reveals the cyclin G2 to suppressss the Wnt/β-catenin Signaling and inhibits gastric cancer cell growth and migration through Dapper1." (PMID 30547803, 2018). "Taken together, these findings reveal that cyclin G2 suppresses Wnt/β-catenin signaling and inhibits gastric cancer cell growth and migration through Dapper1." (PMID 30547803, 2018). "In the present study, we first determined the expression of cyclin G2 in gastric cancer tissues and cell lines." (PMID 30547803, 2018). "Moreover, mutational data were investigated with no major mutations observed; however, there were four synonymous SNPs in Cyclin G2 in gastric cancer samples." (PMID 36769170, 2023). "Therefore, Cyclin G2 and Cyclin L2, along with Cyclin C, are involved in negatively influencing the growth of gastric cancer cells." (PMID 36769170, 2023). "It was concluded that Cyclin G2 downregulation in gastric cancer could be the result of other signaling events involved in the development of gastric cancer." (PMID 36769170, 2023). "Therefore, Cyclin G2 downregulation via miR-340 is one of the mechanisms of how Cyclins are regulated to progress the normal cells to cancerous cells in gastric cancer." (PMID 36769170, 2023). "Furthermore, GSK-3β inhibitors were utilized to explore the role of Wnt/β-catenin signaling in the suppression effect of cyclin G2 on gastric cancer cell proliferation and migration." (PMID 30547803, 2018). "It was reported that expression level of cyclin G2 was correlated with gastric cancer progression." (PMID 30547803, 2018). "However, in DErrico gastric (69 sample) and Ooi gastric (200 cases) datasets, cyclin G2 expression was decreased in gastric cancers." (PMID 30547803, 2018). "Moreover, we showed a relationship between cyclin G2 and β-catenin, the key component of the Wnt/β-catenin signaling, which suggested that cyclin G2 negatively regulate this pathway in gastric cancer." (PMID 30547803, 2018). "Furthermore, immunohistochemical staining of 90 gastric cancer and matched normal tissues revealed that protein levels of cyclin G2 were down-regulated in gastric cancer tissues." (PMID 30547803, 2018).
gastric cancer (continued). "Additionally, Chir99021 abolished the cyclin G2-induced inhibition on SGC-7901 cells proliferation and migration in vitro, suggesting that cyclin G2 inhibited gastric cancer through the Wnt/β-catenin signaling." (PMID 30547803, 2018). "Besides gastric cancer, the potential relationship between low cyclin G2 expression and tumor progression has also been previously reported in oral cancer, esophageal cancer, colorectal cancer, thyroid cancer, epithelial ovarian cancer and prostate cancer." (PMID 30547803, 2018). "Our findings suggest a new mechanism of cyclin G2 in gastric cancer development." (PMID 30547803, 2018). "In addition, miR-340 promoted gastric cancer development by inhibiting CCNG2." (PMID 31013711, 2019). "Therefore, we first determined whether cyclin G2 could inhibit the activity of TOPFlash reporter in gastric cancer cells." (PMID 30547803, 2018). "Thus, further investigation of the biological function of cyclin G2 may provide a molecular basis for the development of candidate therapeutic targets for gastric cancer." (PMID 30547803, 2018). "Consistent with the β-catenin protein level, CHIR99021 attenuated the cyclin G2-induced suppression of cell proliferation and migration of SGC-7901 gastric cancer cells." (PMID 30547803, 2018). "Our findings that cyclin G2 suppressed β-catenin expression and TOP/FOP luciferase activities in gastric cancer cells, as well as in HeLa, HT-29, HEK293 and COS-7 cells, strongly provide evidence that cyclin G2 acts as a suppressor of Wnt/β-catenin signaling." (PMID 30547803, 2018). "Thus, cyclin G2 might be a candidate therapeutic target for gastric cancer treatment." (PMID 30547803, 2018). "The MTS assay and colony formation assays revealed that cell proliferation was inhibited in cyclin G2 overexpressed SGC-7901 and MGC-803 gastric cancer cells, but it was increased in cyclin G2 knockdown cells." (PMID 30547803, 2018). "It is suggested that cyclin G2 could interact with DACT1 and inhibit the ability of CKI to phosphorylate DACT1, thereby stimulating β-catenin degradation in a GSK-3β-dependent in gastric cancer." (PMID 35864965, 2022). "Overexpression of cyclin G2 inhibited the β-catenin/TCF-mediated transcription of SGC-7901 and MGC-803 cells, suggesting that cyclin G2 acted as a negative regulator of the Wnt/β-catenin signaling in gastric cancer cells." (PMID 30547803, 2018). "Besides SGC-7901 and MGC-803 cell lines, we performed a series of experiments to determine the effect of overexpressing cyclin G2 in AGS cells, which is a commonly used gastric cancer cell line, using cell proliferation assay, colony formation assay and transwell assay." (PMID 30547803, 2018). "Moreover, in CCNG2-negative gastric adenocarcinoma and gastric carcinoma, patients had a lower 5-year overall survival rate than those who were CCNG2-positive." (PMID 29720957, 2018). "While the mechanism by which CCNG2 inhibits LPR6 and DVL2 in EOC is not known, a recent report in gastric cancer indicated that CCNG2 downregulated DVL2 through the interaction with Dapper1 (DACT1), a Wnt signalling antagonist that has been shown to promote DVL2 degradation." (PMID 31829231, 2019).